APOE (apolipoprotein E)
Diseases named in the same sentence as APOE in open-access papers (continued):
Sharing a sentence is not in itself a finding about the gene and the disease.
Alzheimer disease (continued). "The apolipoprotein E (APOE) ε4 allele increases the risk of Alzheimer’s disease (AD) such that APOEε4 carriers have a 2 to 15 times greater risk of developing AD." (PMID 39625920, 2024). "Studies of the genetics of Alzheimer’s disease (AD), the most common form of dementia, have identified multiple AD-risk associated loci, the strongest of which is the apolipoprotein E ε4 (APOE ε4) variant." (PMID 38951900, 2024). "Dementia and cognitive function have significant genetic components, with the ε4 allele of the apolipoprotein E (APOE) gene being the strongest genetic risk factor for late‐onset Alzheimer's disease (AD) in many populations." (PMID 38889280, 2024). "The APOE4 variant of apolipoprotein E was identified 30 years ago as the major genetic risk factor for Alzheimer’s Disease (AD) at the population level while the APOE2 variant was the first identified protective allele against AD." (PMID 39528861, 2024). "Brain region segmentation and morphometry in humanized apolipoprotein E (APOE) mouse models with a human NOS2 background (HN) contribute to Alzheimer’s disease (AD) research by demonstrating how various risk factors affect the brain." (PMID 38781243, 2024). "Extensive literature demonstrates that ApoE is the largest genetic risk factor for Alzheimer’s disease (AD)." (PMID 39596576, 2024). "Sleep disorders are prevalent among patients with Alzheimer's disease (AD), and the APOE ε4 genotype is a key genetic risk factor for sporadic AD." (PMID 38421124, 2024). "Alzheimer’s disease (AD) prevalence and severity are associated with increased age, female sex, and apolipoprotein E4 (APOE4) genotype." (PMID 39629477, 2024). "For example, it has been found that the odds ratio of AD in women with one copy of the APOE-ε4 allele is greater than that in men, as reported in a review about sexual dimorphism in Alzheimer’s disease." (PMID 38539590, 2024). "Which isoforms of apolipoprotein E (apoE) we inherit determine our risk of developing late-onset Alzheimer’s Disease (AD), but the mechanism underlying this link is poorly understood." (PMID 38824138, 2024). "Studies using the Alzheimer's Disease Sequencing Project (ADSP) data have identified several other rare APOE variants associated with AD, including the R145C commonly found in the African American AD population." (PMID 39031528, 2024). "Three common isoforms of the apolipoprotein E (APOE) gene - APOE2, APOE3, and APOE4 - hold varying significance in Alzheimer’s Disease (AD) risk." (PMID 39394110, 2024). "APOE4 is a specific variant of the apolipoprotein E (APOE) gene which is considered a major genetic risk factor for late-onset Alzheimer’s disease (AD)." (PMID 38472245, 2024). "The presence of the APOE-ε4 allele(s) is a strong risk factor related to the development of Alzheimer’s disease (AD) (e.g., odds ratio (OR) 5.9 in ε4/ε3 and OR 33.1 in ε4/ε4 in Japanese population), especially of late-onset AD." (PMID 38225507, 2024). "We investigated the associations of the Alzheimer's disease (AD) genetic risk factor APOE and cerebrospinal fluid (CSF) biomarkers Aβ and tau proteins with cognitive and motor phenotype in ALS." (PMID 38853763, 2024). "APOE has been extensively studied for its correlation with neurodegenerative diseases, in particular Alzheimer’s disease (AD), where the possession of the epsilon 4 (E4) allele is established as a risk factor for developing AD in non-familiar sporadic forms." (PMID 39596597, 2024). "The present study aims at detecting behavioral disorders of spatial cognition in prodromal Alzheimer’s disease (AD) and verifying the association between Apolipoprotein E-ε4 (ApoE-ε4) genotype and gait patterns during a real-world naturalistic task." (PMID 39336934, 2024). "Increasing evidence supports that age, APOE and sex interact to modulate Alzheimer’s disease (AD) risk, however the underlying pathways are unclear." (PMID 38020764, 2023).
Alzheimer disease (continued). "APOE genotype is associated with an increased risk for several diseases, including Alzheimer’s disease and synucleinopathies." (PMID 37479568, 2023). "The design of the software and its potential uses are described, and a demonstration is presented in the discovery of modifier alleles of the ApoE gene in affecting Alzheimer's disease (AD) by analyzing the UK Biobank dataset." (PMID 36322888, 2023). "These high-risk patients possessed a family history of Alzheimer diseases and were ApoE ε4 carriers." (PMID 36983883, 2023). "APOE is involved in lipid metabolism and is a major genetic risk factor for late-onset Alzheimer’s disease, with the APOE ε4 allele being particularly associated with an increased risk." (PMID 37965040, 2023). "Apolipoprotein E (ApoE) ε4 genotype is the most prevalent risk factor for late-onset Alzheimer’s Disease (AD)." (PMID 37280636, 2023). "The most-validated risk factor for developing the late form of Alzheimer's disease is the presence of the E4 allele of the APOE gene (APOE4)." (PMID 37396132, 2023). "Apolipoprotein E (ApoE) genotype has been extensively studied in the context of Alzheimer’s disease as a potential genetic risk factor." (PMID 37693748, 2023). "Possession of the TNF-alpha T allele significantly increases the risk of vascular dementia and increases the risk of Alzheimer’s disease associated with apolipoprotein E (APOE)." (PMID 37570816, 2023). "The genetic analysis employed in the longitudinal study to assess the risk of developing Alzheimer’s disease focuses on the APOE e4 allele." (PMID 38125832, 2023). "The apolipoprotein E (ApoE) gene is a genetic risk factor for late-onset Alzheimer’s disease, in which ε4 allele carriers have increased risk compared to the common ε3 carriers." (PMID 37298071, 2023). "Plasma apolipoprotein E levels were previously associated with the risk of developing Alzheimer’s disease (AD), levels of cerebrospinal fluid AD biomarkers, cognition and imaging brain measures." (PMID 36720957, 2023). "It has been suggested that low plasma levels of APOE are linked to an elevated risk of developing future Alzheimer's disease and all forms of dementia in the general population." (PMID 37455936, 2023). "Growth conditions have been refined for phenolic induction, then tested in stressed primary cultures derived from a mouse APOE gene replacement model of low, average, and high risk of developing Alzheimer’s Disease (AD)." (PMID 38115032, 2023). "Apolipoprotein (APOE) E4 isoform is a major risk factor of Alzheimer’s disease and contributes to metabolic and neuropathological abnormalities during brain aging." (PMID 37337279, 2023). "High levels of VGF are protective against the development of Alzheimer’s disease generally, and on an APOE E4 risk background there is approximately a 50% reduction in the proportion of individuals with LOAD when there are high levels of VGF (yellow box)." (PMID 38168398, 2023). "The Apolipoprotein E (APOE) locus has garnered significant clinical interest because of its association with Alzheimer’s disease (AD) and longevity." (PMID 37445616, 2023). "ApoE allelic variants are associated with an increased risk for Alzheimer’s disease and cognitive decline in PD." (PMID 37479568, 2023). "Apolipoprotein E4 (APOE4) is the strongest genetic risk factor for late-onset Alzheimer’s disease (LOAD), leading to earlier age of clinical onset and exacerbating pathologies." (PMID 37957317, 2023). "Polymorphism of the ApoE gene is a major risk for Alzheimer’s disease, with the strongest risk being for the ε4 allele associated with lower levels of ApoE, while the ε2 allele is protective with higher levels of ApoE." (PMID 36980195, 2023). "The ApoE protein is considered a major risk factor for some amyloid-related diseases, including Alzheimer’s disease (AD), Parkinson’s disease (PD), Transmissible spongiform encephalopathies (TSEs), type 2 diabetes (T2D)." (PMID 36817952, 2023).
Alzheimer disease (continued). "APOE ε4 isoform is the strongest genetic risk factor for Alzheimer’s disease, and it has neuropathological effects on neurons and the blood-brain barrier resulting in various clinical manifestations after brain injury." (PMID 36640294, 2023). "The apolipoprotein E (APOE) gene is a major risk factor for developing late-onset Alzheimer’s disease, which more frequently appears after the age of 65 years." (PMID 36991494, 2023). "APOE polymorphism is the most common genetic risk factor for late‐onset Alzheimer's disease where the ε4 genotype is associated with a significantly earlier disease onset compared to the neutral ε3 allele." (PMID 36709412, 2023). "Possession of one copy of the APOE-ε4 allele confers a 3-fold increase in risk while two copies confer a 15-fold increase, making APOE-ε4 status the strongest genetic predictor of Alzheimer’s disease risk." (PMID 38048316, 2023). "This mapped to the APOE gene, where rs429358 is a missense mutation, with the C-allele of the APOE-ε4 genotype being a major risk factor for Alzheimer’s disease." (PMID 37945700, 2023). "The ε4 isoform of APOE is associated with increased total cholesterol and low-density lipoprotein cholesterol, heart disease, Alzheimer’s disease and dementia and other illnesses." (PMID 36735720, 2023). "For example, studies have shown that the APOE e4 allele, the major risk factor for Alzheimer’s disease (AD), is associated with worse neurocognitive outcomes in some cancer patients." (PMID 37296840, 2023). "The Apolipoprotein E (ApoE) gene has been primarily studied in the context of its association with Alzheimer’s disease." (PMID 37626936, 2023). "The polygenic risk score (PRS), together with the ɛ4 allele of the APOE gene (APOE-ɛ4), has shown high potential for Alzheimer’s disease (AD) risk prediction." (PMID 37834213, 2023). "Currently, testing for the genetic susceptibility to cognitive disorders, particularly Alzheimer’s disease, in older adults relies on early detection of the APOE ε4 allele." (PMID 37953886, 2023). "Of note, higher apoE in whole plasma and a higher apoE content in HDL particles were associated with lower dementia risk and, conversely, reduced plasma ApoE plus the APOE ε4 allele were associated with elevated risk for Alzheimer’s disease." (PMID 36980195, 2023). "The age and sex stratified association between Alzheimer’s disease and APOE ε4 allele and genotypes." (PMID 37680541, 2023). "The APOE-4 allele has been identified as a significant risk factor for both Alzheimer’s disease (AD) and obstructive sleep apnea (OSA)." (PMID 37761265, 2023). "Changes in the structure of the APOE protein, caused by a single-nucleotide substitution, alter its biophysical and biochemical properties, possibly accounting for its association with Alzheimer’s disease." (PMID 37953886, 2023). "Among ApoE’s allelic variants (ε2, ε3, ε4), the ε4 allele, encoding the ApoE4 isoform, carries the most significant risk for the development of the late-onset Alzheimer’s disease." (PMID 36710921, 2023). "Possession of the APOE4 isoform is the greatest risk factor for Alzheimer’s disease, and APOE dysfunction is related to coronary heart disease." (PMID 36830724, 2023). "PRS can be used to estimate penetrance and recurrence risk in familial Alzheimer's disease among carriers and non‐carries of APOE‐ε4." (PMID 36946865, 2023). "A recent investigation even revealed that disruptions in gut microbiome composition can modify immune pathways, leading to the tauopathy underlying Alzheimer’s disease in an APOE genotype-dependent manner." (PMID 37736325, 2023). "This indicates that affected siblings in the highest PRS quintile confer approximately 70% additional lifetime risk of Alzheimer's disease to their co‐sibling and together with the APOE alleles explains nearly half of the recurrence risk." (PMID 36946865, 2023).
Alzheimer disease (continued). "It is considered the third most prominent genetic risk factor for late-onset Alzheimer’s disease, just after apolipoprotein E (APOE) and bridging integrator 1 (BIN1)." (PMID 37240249, 2023). "For example, the lipid transport gene APOE, which is a major risk gene for Alzheimer’s disease, showed high expression variability (0.74) while being widely expressed (φ = 0.87), and this gene has been labeled as both a UEG or SEG by several studies." (PMID 35569803, 2023). "We focused on APOE, as it is the main risk factor for Alzheimer’s disease, a disease associated with compromised mitochondrial function." (PMID 37171075, 2023). "The ε4-allele variant of apolipoprotein E (ApoE4) is the strongest genetic risk factor for Alzheimer’s disease, although it only differs from its neutral counterpart ApoE3 by a single amino acid substitution." (PMID 36749730, 2023). "For individuals in the highest PRS quintile, the recurrence risk of Alzheimer's disease was 17%, but it increased to 19% when including the APOE alleles in the PRS score." (PMID 36946865, 2023). "Apolipoprotein E (apoE), a major apolipoprotein involved in lipoprotein metabolism, is closely associated with lipid levels, cardiovascular risk, and Alzheimer disease." (PMID 37641103, 2023). "Apolipoprotein E levels also appeared to be associated with both cognitive impairment and Alzheimer’s disease and dementia." (PMID 37108152, 2023). "The ε4 allele of the apoE gene increases the risk of Alzheimer’s disease, while the ε2 allele provides protection against it." (PMID 36830968, 2023). "The ε4 allele of the Apolipoprotein E gene (APOE4) is a well-known genetic risk factor for late-onset Alzheimer’s disease." (PMID 37699966, 2023). "Alzheimer’s disease (AD) is a highly prevalent neurodegenerative disease, and its primary risk factors include advanced age, the APOE ε4 allele, and being female." (PMID 37107675, 2023). "For instance, Apolipoprotein E (APOE) is involved in lipid transport and neural health, and is strongly linked to multiple age-related traits including Alzheimer’s disease, cardiovascular disease, stroke, and longevity." (PMID 37749083, 2023). "Recent investigations into synucleinopathies with cognitive features have uncovered curious connections to a major Alzheimer’s disease (AD)—associated gene, apolipoprotein E (APOE; HGNC:613)." (PMID 37482615, 2023). "The most well-known genetic risk factor for Alzheimer’s disease is the Apolipoprotein E ε4 (ApoE4) allele." (PMID 37299431, 2023). "This is the case, for example, for the epsilon 4 allele of the apolipoprotein E (APOE) gene involved in fat metabolism where a subtype of the APOE gene is involved in Alzheimer’s disease and in cardiovascular diseases." (PMID 36673670, 2023). "APOE is the largest genetic risk factor for sporadic Alzheimer’s disease (AD), but there is a substantial polygenic component as well." (PMID 36909609, 2023). "APOE-ɛ4 risk on Mild Cognitive Impairment (MCI) and Alzheimer’s Disease (AD) differs between race/ethnic groups, presumably due to ancestral genomic background surrounding the APOE locus." (PMID 36991100, 2023). "We uncovered a significant enrichment for processes regulating amyloid-beta formation, revealing that hc-RAE expression impacts Alzheimer’s disease risk genes that include APOE, ABCA7, CLU, NTRK2, and more." (PMID 36640362, 2023). "Previous publications have suggested a possible role of APOE in conferring protection or risk of more severe clinical manifestations of COVID-19, with similar physiopathology processes already described in Alzheimer’s disease (AD)." (PMID 38137059, 2023). "Aging, female sex and Apolipoprotein E ε4 (APOE4) genotype are the strongest risk factors for late-onset Alzheimer’s disease (AD)." (PMID 36787293, 2023).
Alzheimer disease (continued). "Although the ε4 allele of the apolipoprotein E (ApoE4) gene has been established as a genetic risk factor for many neurodegenerative diseases, including Alzheimer’s disease, the mechanism of action remains poorly understood." (PMID 36720919, 2023). "The association between Alzheimer’s disease and APOE ε4 allele and genotypes in Taiwanese participants." (PMID 37680541, 2023). "APOE ɛ4 is a variant of the APOE gene that is associated with an increased risk for developing Alzheimer’s disease." (PMID 37485386, 2023). "Carrying the ε4 allele of the APOE gene is the strongest risk factor for late-onset Alzheimer’s disease, while carrying the ε2 allele is protective." (PMID 36991494, 2023). "APOC1 and APOE are both located within the 19q13.2 locus and are well-known risk factors for Alzheimer’s disease." (PMID 36882310, 2023). "For instance, ApoE is a well-known gene carrying risk for Alzheimer’s disease, while COMT has been associated with age-related reductions in motor function." (PMID 37744392, 2023). "The most well-known genetic risk factor for dementia is the apolipoprotein E (APOE) gene, with certain variations of this gene, particularly APOEε4, strongly associated with an increased risk of Alzheimer's disease." (PMID 38074067, 2023). "ApoE is an established genetic risk factor for Alzheimer’s disease with roles in Aβ clearance, glucose metabolism and proinflammatory responses." (PMID 37351595, 2023). "In an early study we reported, the risk of dementia, both Alzheimer’s dementia (AD) and Vascular dementia (VaD), in those with an APOE Ɛ4 haplotype was 3–4 times higher (OR: 3.72 in AD and 2.72 in VaD)." (PMID 38028602, 2023). "Apolipoprotein E (Apo-E) is a protein involved in the transport and metabolism of fats in the bodies of mammals, and has been implicated in Alzheimer’s disease." (PMID 36980304, 2023). "Apolipoprotein E4 (ApoE4) is the most recognized genetic risk factor for late-onset Alzheimer’s disease (LOAD), whereas ApoE2 reduces the risk for LOAD." (PMID 36766752, 2023). "Carrying the apolipoprotein E (ApoE) Ɛ4 allele is associated with an increased risk of cerebral amyloidosis and late-onset Alzheimer’s disease, but the degree to which apoE glycosylation affects its development is not clear." (PMID 37221560, 2023). "While mitochondrial dysfunction is acknowledged as an important factor in Alzheimer’s disease, mitochondria are typically placed downstream of Aβ and APOE, with Aβ or the APOE4 allele perturbing mitochondrial function." (PMID 37171075, 2023). "On the contrary, they have failed to impact on cognition in individuals with mild–moderate Alzheimer’s disease carrying the ε4 allele of apolipoprotein E, an established risk factor for late-onset Alzheimer’s disease." (PMID 36834804, 2023). "The comparison of APOE ε4 allele frequency in patients with Alzheimer’s disease and the related risk for Alzheimer’s disease among different ethnicities." (PMID 37680541, 2023). "The most serious risk factors for Alzheimer’s disease are advanced age and having at least one apolipoprotein E (APOE) epsilon 4 allele." (PMID 36845144, 2023). "Despite being identified as the strongest genetic risk factor for Alzheimer’s disease more than 20 years ago, a connection between the biochemical properties of apolipoprotein E (ApoE) and its role in the disease remains elusive." (PMID 36749730, 2023). "Conversely, APOE ε2 is associated with a lower risk of Alzheimer’s disease but poorer kidney function." (PMID 37605228, 2023). "Another study has demonstrated that in carriers of the main susceptibility gene for Alzheimer's disease (E4 variant of apolipoprotein E), breakdown of the BBB contributes to cognitive decline independently of Alzheimer's disease pathology." (PMID 36929707, 2023). "The APOE-ε4 allele has been linked with substantial increases in the risk of developing late-onset Alzheimer’s disease." (PMID 38048316, 2023).